GZMB (granzyme B)
Diseases named in the same sentence as GZMB in open-access papers (continued):
Sharing a sentence is not in itself a finding about the gene and the disease.
tumor (continued). "CD4 CTLs are a CD4 subset with cytotoxic activity and can directly kill tumor cells by secreting granzyme B and perforin, while Th2 and Th17 cells inhibit cell-mediated immunity and promote tumor progression." (PMID 34209797, 2021). "From a mechanistic point of view, iNKT cells, similarly to other cytotoxic populations, are known for inducing tumor cell death both by granzyme B/perforin production and by expression of Fas ligand (FasL) and TRAIL on their plasma membranes." (PMID 34535957, 2021). "The T-cell engaging CD3-bispecific antibody, PF-07062119 treatment shows dose-dependent efficacy and significant tumor recruitment of engrafted T cells with polarized Granzyme B signal by IHC in this model." (PMID 34143379, 2021). "Consistently, the MDSCs were decreased but the CD8+ T cells and granzyme B increased in the tumor tissues of mice given CXCR2 antagonist." (PMID 34108444, 2021). "Functional lytic synapses between NK cells and tumor cells are characterized by polarization of F-actin toward the synapse interface, as well as localization of granzyme B+ lytic granules at the synapse." (PMID 33621210, 2021). "The results showed that the levels of both cleaved-caspase-3/pro-caspase-3 and granzyme B in tumor tissues were significantly elevated when f 50 or 100 mg/kg body weight of theacrine was supplemented daily to rats after DMBA treatment." (PMID 34946538, 2021). "Cytotoxic T cell exerted antitumor effects via cytokine production, such as IFN-γ, TNF-α, granzyme B, and perforin, under the specific tumor antigen stimulation." (PMID 34381711, 2021). "CD8 + CD56+ natural killer T (NKT) cells are a natural and unique subset of lymphocytes in humans that present characteristics of T and NK cells and exert cytotoxicity on tumour cells in a granzyme B-dependent manner." (PMID 34332557, 2021). "Our study showed higher expression of Ki67, CD107a, GzmB and IFN-γ in the tumor-infiltrating CD8+ T cells from PVRIG-deficient mice, suggesting that besides NK cells, CD8+ T cells in PVRIG-deficient mice were also more functional." (PMID 34174928, 2021). "In HSC4-bearing huNOG-FcγR−/− mice, nivolumab induced both infiltration of T cells into tumor and increases of T-cell subpopulations expressing various cytokines or cytotoxic molecules, which include GZMB, IL-2, or IFN-γ." (PMID 34702924, 2021). "Degranulation, granzyme B, NK cell-tumour cell conjugates and ligands profiling were detected by flow cytometry." (PMID 33399495, 2021). "Collectively, our results confirm that probe 1 provides a direct optical readout of NK cell activity against tumours via detection of active granzyme B, either in the extracellular milieu or intracellularly in target cancer cells." (PMID 33300671, 2021). "The overall expression of granzyme B within tumor microenvironment has been well-established as a prognostic marker indicative of priming immunity for a long time." (PMID 33868318, 2021). "The spot-form cells (SFC)/105 of CD8+ T cells of perforin and granzyme B was also remarkably decreased in GC patients (both peripheral and tumor-infiltrating) when compared with in NC (LSD-t test, all P < 0.0001)." (PMID 34620075, 2021). "Basophils express cytotoxic molecules, such as granzyme b, and can have cytotoxic effects on tumor cells." (PMID 35008239, 2021). "The infiltration of CD4+ GzmB+ T cells in the tumor center had a significant prognostic value, positively correlated with good OS and DFS." (PMID 34631551, 2021). "Low tumor uptake will hamper the utility of granzyme B peptides in tumors located in organs with higher background such as those organs associated with peptide excretion including the bladder and kidneys and to a lesser extent the liver and intestines." (PMID 33713000, 2021). "Granzyme B+CD8+ cytotoxic T cells were significantly increased following neutron irradiation compared to X-ray irradiation in WT tumor models." (PMID 34680381, 2021).
tumor (continued). "In this study, we explored granzyme B (GZB), released by tumor-associated immune cells, as a PET imaging-based stratification marker for successful combination therapy using a fluorine-18 (18F)-labelled GZB peptide ([18F]AlF-mNOTA-GZP)." (PMID 33713000, 2021). "The CD8+ T cells are able to recognize and eliminate tumor cells mainly through perforin and granzyme B pathways." (PMID 33995619, 2021). "The adoptive transfer of PD-1−/− DCs increases CD8+T-cells infiltrations along with IFNγ, IL-2, perforin and GZMB secretions in the TME and thereby causing rapid tumor control." (PMID 34571899, 2021). "CD8+T cells combine with T cell receptors to produce interferon-γ (IFN-γ), tumor necrosis factor (TNF) and granzyme B, which targets tumor cells and results in tumor cell clearance." (PMID 34777372, 2021). "For a long time, granzyme B has been well-accepted as a representative marker for the priming of immunity and efficient killing of tumor cells." (PMID 33868318, 2021). "Consistent to that, both the granzyme B and perforin expression level, the markers of cytotoxicity of immunocytes, were found to be increased in tumor tissues of PHA-L-treated as well as 130 kD protein-treated mice compared with that in control mice." (PMID 33477737, 2021). "To determine the immunological effect of GM-CSF in vivo, we further examined the tumor-infiltrating lymphocytes (TILs) and its activation marker (granzyme B) in tumor tissues derived from mice." (PMID 34051805, 2021). "CD8+ T cells produce IFNγ, TNF and granzyme B by binding to T cell receptors and tumor cells, leading to tumor cell clearance." (PMID 34603277, 2021). "Sarcomatoid tumors show fewer CD4+ and CD8+ T cells in the tumor and are characterized by a loss of Th1 features such as T-bet (marker for Th1 polarization) and granzyme B expression, which are required for an efficacious anti-tumor immune response." (PMID 34249695, 2021). "NK cells kill tumor cells via release of cytotoxic mediators perforin and granzyme b or to a less degree via the interaction of NK cell FasL with the Fas receptor on tumor cells." (PMID 33995369, 2021). "In T cells, we demonstrated that the CM of RV‐treated or fused B16 cells markedly reduced the production of IFN‐γ and granzyme B in T cells activated through the T‐cell receptor mimicking the dysregulation state of tumor‐infiltrating T cells in humans." (PMID 34698427, 2021). "Only when these escape mechanisms are not yet engaged can CTLs become activated by recognizing tumor antigens and produce effector molecules, such as Perforin and Granzyme B, that lead to tumor cell elimination." (PMID 34359741, 2021). "We further explored the expression of cytotoxic factors, including interferon γ (IFN-γ), tumor necrosis factor α (TNF-α) and granzyme B, in the tumor-infiltrating T cells." (PMID 34373258, 2021). "NK cells represent another important cell type in immune-mediated tumor killing through granzyme B- and perforin-mediated apoptosis or Fas–Fas ligand interactions." (PMID 34831167, 2021). "Because the enzymatic activity of granzyme B is directly related to the cell death initiated by NK cells, this probe behaves as a direct reporter of the host's immune cytotoxicity in tumours." (PMID 33300671, 2021). "CD56dimCD16− NK cells infiltrating tumor tissue also exhibited reduced expression of GzmB and perforin compared with paired PBMC." (PMID 34187852, 2021). "B cells have been shown to promote anti-tumour immunity through the release of inflammatory cytokines, such as IFNγ and IL-12, and directly attack tumour cells via production of granzyme B and TRAIL in hepatocellular carcinoma." (PMID 34885021, 2021).
tumor (continued). "Compared to bystander memory T cells, the tumor-specific TIL exhibited significantly higher expression levels of GzmB, PD-1, TIM-3, and significantly lower expression levels of Bcl-2, and significantly reduced proportions of CD62L+ cells." (PMID 34867942, 2021). "Collectively, however, these results suggest that trichosanthin and granzyme B combination treatment was superior to either drug alone for inhibiting SCC25 tumor growth in vivo." (PMID 33750370, 2021). "Even after NK cell recognition of tumor cells, hypoxia-induced autophagy in cancer cells leads to degradation of granzyme B, rendering NK cells in hypoxic tumor microenvironments less cytotoxic." (PMID 33766099, 2021). "Immunostaining with anti‐GzmB demonstrated that circFat1 KD plus anti‐PD1 also recruited more GzmB+ CD8+ T cells into tumor tissues compared with anti‐PD1 or circFat1 KD alone." (PMID 34258151, 2021). "Granzyme B (GZMB) is generally produced in the tumor microenvironment by cytotoxic T lymphocytes (CTLs) and natural killer (NK) cells as a toxic granule-secreted enzyme with killing activity." (PMID 33898319, 2021). "It appears the required events that determine tumor infiltration are different from those needed for the differentiation of T cells leading to Granzyme B expression." (PMID 34142056, 2021). "Tumor-associated lineage−CD45+CD33+ MDSCs from high-grade ovarian serous cancer patients suppress proliferation of T cells and inhibit their function through downregulating the expression of IL-2, INF-γ, and granzyme B, resulting in increased tumor volume." (PMID 34359674, 2021). "iNKT cells have the capacity to mediate direct cytolytic activity against CD1d positive tumor cells via perforin, granzyme B, and TNF-related apoptosis-inducing ligand (TRAIL) pathways." (PMID 34680322, 2021). "Blockade of mast-cell-associated PD-L1 resulted in enhanced tumor control, CD3 T-cell infiltration, as well as increased IFN-γ and granzyme B production." (PMID 34063789, 2021). "The immune surveillance is responsible for infections and is currently found to potentially eradicate tumors: CD8+ T cells recognize tumor cells and secrete granzyme B (GZMB) and perforin (Prf1) to elicit tumor cell apoptosis and death." (PMID 34685495, 2021). "Hypoxic tumor cells can use autophagy to their advantage and selectively degrade the NK cell-released granzyme B, which is responsible for NK-mediated apoptosis of target cells." (PMID 33422072, 2021). "We also confirmed increased staining for perforin (p < 0.01) and granzyme B (p < 0.05) at the tumor site of animals treated with the IRIN silicasome compared to free drug or the saline control." (PMID 33747719, 2021). "In light of the anti-tumor reputation of granzyme B, the development of GrB-based/targeted theranostics has been advanced rapidly in recent years." (PMID 33868318, 2021). "Though granzyme B demonstrates pleiotropic effects in different hosts, excessive expression of granzyme B within the same context has been proved to culminate in anti-tumor propensity due to its innate cytotoxicity." (PMID 33868318, 2021). "Other potential serum biomarkers under investigation include circulating tumor cells (CTCs), tumor mutational burden (TMB), circulating tumor DNA (ctDNA), soluble Granzyme B, microRNA (miRNA), blood microbiome, and exosomes." (PMID 34503087, 2021). "In liver metastases (LM), the intra-tumoral densities of CD163+ tumor-associated macrophages (TAM) and of total CD8+ T cells were higher than in extra-hepatic UM metastases, but the percentage of Granzyme B+ CTL was lower." (PMID 33947438, 2021). "Further investigation into the impact of vanadyl sulfate plus NDV combination therapy on the cytotoxic potential of NK cells revealed the highest percentage of granzyme B+ NK cells in the tumor in the combination therapy group at the 24 h time point." (PMID 33614913, 2021).
tumor (continued). "NK cells recognized major histocompatibility complex class I (MHC-I) on the surface of tumor cells and secreted perforin and granzyme B to induce tumor cell death." (PMID 35242027, 2021). "The results from RNA in situ hybridisation (ISH) showed a large number of infiltrating CAR T cells with significantly elevated expression of IFN-γ, granzyme B and FasL in the tumour sites on day 14 after infusion in the dCAR T group." (PMID 33462245, 2021). "Consistent with this, TCRβ sequencing demonstrated that OT-1 was the most abundant T-cell clone in both blood and tumors, and treatment with mRBC-OVA-4-1BBL-IL-12 increased the percentage of polyfunctional (granzyme B+IFNγ+) tumor-infiltrating OT-1 cells." (PMID 33976146, 2021). "The expression of Granzyme B in the tumor tissues resected from each mouse was measured by Western blot to evaluate the functions of immune cells." (PMID 33934451, 2021). "Immunohistochemical analysis showed that the combination treatment increased both the number of CD8+ TILs and granzyme B production in B16-F10 tumour tissue compared with treatment with nintedanib alone." (PMID 33299131, 2021). "Consistent with increased tumor-infiltrating lymphocytes (TILs) in tumors, CA170 plus KVax treatment also increased the expression of IFN-γ, TNFα, and granzyme B in tumor-infiltrating CD4+ and CD8+ T cells in tumors." (PMID 34302042, 2021). "Those subset CD8+ T cells expressing IFN-γ marker associated with Cytotoxic T lymphocytes (CTL), Granzyme B expression also serve as a signature of CTL activation, which can directly kill tumor cells and play a very important role in antitumor immunity." (PMID 34025668, 2021). "Considering the predominance of effector T cells in the setting of anti-tumor immunity, AICD is supposed to be a primary cause for granzyme B-mediated immunosuppression." (PMID 33868318, 2021). "Activated γδ T cells also produce cytolytic proteins Granzyme B and Perforin, through which they lyse the tumor cells after migrating to the tumor microenvironment." (PMID 34526984, 2021). "They showed how EA increases the number of NK cells in peripheral blood, infiltrates the tumour, and increases granzyme B and perforin in the tumour tissue." (PMID 34831327, 2021). "Some argued that cytotoxic CD4+ T cells regulated the tumor rejection in a cytolytic molecules-dependent way (e.g., perforin, granzyme B)." (PMID 34631551, 2021). "Remarkably, it is important to highlight that we found a low number of CD8 Granzyme B cells compared to CD8+ cells in the tumor portion." (PMID 34484217, 2021). "NK cells can realize cytotoxic potential against tumor cells via both the granule-mediated cytotoxicity mechanism involving perforin and granzyme B, and the receptor-mediated mechanism through cytokine TRAIL release, or the expression of surface FasL." (PMID 34768814, 2021). "Immune factor including IFN-γ, granzyme B and IL-15 in both tumor tissues and (or) serum were also elevated." (PMID 34593005, 2021). "By IHC analysis, we found that transfection of sh‐c‐Myb into FLO‐1 cells increased CD3 and Granzyme B expression in the tumor tissues." (PMID 34586738, 2021). "MAIT cells from responders express higher level of CXCR4 and produce more granzyme B. In silico analysis support MAIT presence in the tumor microenvironment." (PMID 33723257, 2021). "Nevertheless, the detailed interaction between Granzyme B in MDSCs and the promotion of tumor growth still keep in the dark and warrant further investigation." (PMID 33868318, 2021). "After deleting perforin/GzmB in MDSCs in vivo, an increased amount of CD8+ T cells appeared in the tumor lesion together with better therapeutic performance, suggesting an immunosuppressive role of granzyme B from MDSCs." (PMID 33868318, 2021). "Eosinophils are activated by IL33, IFN-γ, and IL-5, and activated eosinophils secrete MBP, tumor necrosis factor (TNF)-α, eosinophil peroxidase, and granzyme B, which facilitate the killing of tumor cells." (PMID 35011007, 2021).
tumor (continued). "In this paper, the granzyme B-related regulatory effects of major suppressor cells as well as the tumor microenvironment that defines such functionalities were longitudinally summarized and discussed." (PMID 33868318, 2021). "The levels of total and activated CD8+ cytotoxic T cells (GzmB+) that infiltrated the tumor microenvironment were significantly increased in the ARIH1-OE group." (PMID 33879767, 2021). "The protein levels of perforin and granzyme B in lymphocytes isolated from H22 tumor-bearing mouse livers were markedly higher than those in the control group." (PMID 33710817, 2021). "Targeting immune cells is important; indeed, the combination of a CD40 agonist and a PD-1 antagonist MAb exerts anti-tumor effects, which are manifested through tumor infiltration by IFNγ-, Granzyme B-, and TNFα-secreting effector T cells." (PMID 34439378, 2021). "The new granzyme B tracer, dependent on proteolytic activity, shows higher tumour retention, but due to its considerable size is cleared much more slowly from blood, leading to higher background." (PMID 35936114, 2021). "IFNγ+ CD8+ T cells contain subsets that expressed tissue-resident memory T cell marker CD103, and granzyme B (GrB), a key effector molecule of cytotoxic T cells, and are therefore capable of inducing an anti-tumour response." (PMID 34658896, 2021). "Tumor samples of mice treated by GM-CSF had significantly higher level of granzyme B than IgG group." (PMID 34051805, 2021). "IHC staining showed that the tumour-infiltrating CD8+/Granzyme B (GZMB) + T lymphocytes were greatly increased in mGDF1-transfected tumours after anti-PD1 therapy." (PMID 34880251, 2021). "Further analysis demonstrated tumor-infiltrating cells from GSK-3 double cKO mice to have higher levels of granzyme B expression compared to the single cKO mice." (PMID 34142056, 2021). "Cell–cell contact between tumor cell and NK cell, mediated by a variety of receptors including NKG2D promote activation and release of proteins including perforin and granzyme b which directly destroy tumor cells." (PMID 34832522, 2021). "In responders post-treatment, PD-1+ CD4+ T cells increase GZMB expression and move closer to tumor cells, similar to the granzyme-perforin-dependent tumor-killing mechanism used by cytotoxic CD8+ T cells." (PMID 34795254, 2021). "Consecutively, CTLs are capable to kill tumor cells by the release of perforins and granzyme B or by a mechanism that involves Fas ligand (FasL, CD95L)-mediated apoptosis of target cells." (PMID 34135885, 2021). "Overall, [18F]AlF-mNOTA-GZP demonstrates the ability to accurately stratify ICI response in HCCs, showing that granzyme B radiopharmaceuticals can be used across multiple tumour types, including those arising in immune suppressive environments." (PMID 35936114, 2021). "The killing ability of Vγ2Vδ2 T cells induced by Y111 prompted us to check the production of killing cytokines, including IFNγ and TNFα, and cytotoxic mediator granzyme B in the co-culture of the T cell and tumor cells." (PMID 34040604, 2021). "CD8+ T cells produce IFN-γ, TNF and granzyme B by binding T cell receptors to target tumor cells, leading to tumor cell clearance." (PMID 34305884, 2021). "But that study did not go deep into detailed investigations of regulation networks around granzyme B. Another noteworthy issue is some tumor cells are observed with endogenous granzyme B and suspect of expressing such proteinase themselves." (PMID 33868318, 2021). "To link the observed increase in tumor infiltrating T cells with effector T cell function we stained tumors for granzyme B and show increased expression of granzyme B in PAG KO tumors." (PMID 34083754, 2021). "We found that neoadjuvant chemotherapy promoted the infiltration of CD4+ GzmB+ T cells, B cells and granulocytes in the central region of the tumor, thus improving the tumor immune microenvironment." (PMID 34631551, 2021).